CRP (C-reactive protein)
Diseases named in the same sentence as CRP in open-access papers (continued):
Sharing a sentence is not in itself a finding about the gene and the disease.
sarcopenia (continued). "One of these is that none considers laboratory or radiographic factors that could influence frailty, such as C-reactive protein, interleukins or radiographic indices of sarcopenia\osteopenia." (PMID 38382093, 2025). "This study aimed to investigate the association between the high-sensitivity C-reactive protein/high-density lipoprotein cholesterol (Hs-CRP/HDL-C) ratio and sarcopenia among U.S. population by using composite marker integrating systemic inflammation and lipid metabolism." (PMID 40672942, 2025). "The MSS group presented with the highest CRP levels, followed by the sarcopenia-alone group." (PMID 41323996, 2025). "CRP was significantly elevated in patients with sarcopenia (p = 0.035)." (PMID 40430249, 2025). "Patients with sarcopenia had higher levels of CRP and ESR at diagnosis and six-month follow-up." (PMID 40476129, 2025). "Notably, most patients diagnosed with sarcopenia have diffuse cutaneous SSc and elevated CRP concentrations, suggesting a potential connection between sarcopenia and increased systemic inflammation." (PMID 40422566, 2025). "Based on this knowledge, we speculated that the CRP/albumin ratio might be an even better marker of inflammation than CRP or albumin alone in relation to nutritional status and sarcopenia." (PMID 41345186, 2025). "Sarcopenia correlation with CRP and ESR at one and six-month follow-up." (PMID 40476129, 2025). "This study aimed to assess the efficacy of a novel modified Geriatric Nutritional Risk Index (mGNRI), which incorporates C-reactive protein (CRP) levels and weight changes, in predicting sarcopenia compared to traditional indices (geriatric nutritional risk index, GNRI/nutritional risk index, NRI)." (PMID 41262732, 2025). "Elevated CRP values, commonly associated with infection, were also linked to worse outcomes in cirrhotic patients with both sarcopenia and frailty compared to those without both of these complications (p = 0.0039)." (PMID 39795544, 2024). "Furthermore, studies have highlighted the correlation between inflammatory status and sarcopenia, showing a positive relationship between levels of C-reactive protein, interleukin-6, and sarcopenia." (PMID 39797093, 2024). "In the current nationwide cross-sectional study, CRP levels showed a nonlinear association with sarcopenia among the US adult population." (PMID 39969369, 2024). "Besides, to elucidate the relationship between serum CRP levels and sarcopenia-related traits, we employed Spearman rank correlation test." (PMID 39502753, 2024). "The relationship between the MAFLD and sarcopenia were mediated by CRP and HDL cholesterol." (PMID 38491346, 2024). "The mediation effect of glucosamine on cognition, and sarcopenia-related traits via CRP." (PMID 39764251, 2024). "In addition, our analyses were adjusted for several crucial confounders of nutritional and inflammatory status, including serum calcium level, MIS, and hs-CRP level, all of which are relevant to the prognosis of sarcopenia." (PMID 38351264, 2024). "A meta-analysis published in 2016 indicated that sarcopenia is associated with increased C-reactive protein (CRP) levels but did not confirm the association between sarcopenia and interleukin-6 (IL-6) or tumour necrosis factor α (TNF-α) concentrations." (PMID 38398421, 2024). "However, other studies have shown that C-reactive protein (CRP) and lesion location (L2 type) are associated with the development of sarcopenia." (PMID 38438954, 2024). "Notably, two recent meta-analyses have demonstrated a correlation between the inflammatory marker CRP and sarcopenia." (PMID 39458423, 2024). "The validity of CRP as a sarcopenia predictor was further corroborated by ROC curve analysis." (PMID 39502753, 2024). "Thus, it is necessary to consider the possible role of CRP levels in sarcopenia when treating and preventing these conditions." (PMID 39969369, 2024).
sarcopenia (continued). "Univariate analysis revealed a significant reduction in overall survival in patients with a prognostic nutritional index of <45, C-reactive protein-to-albumin ratio of ≥0.047, cancer antigen 19–9 levels of ≥130 U/mL, sarcopenia, lymph node metastasis, and vascular invasion." (PMID 38913646, 2024). "Therefore, in the mediation study, we explored the mediating effect of CRP and BMR on the causality between glucosamine and indicators of cognition and sarcopenia." (PMID 39764251, 2024). "Based on our results, CRP levels showed a nonlinear association with sarcopenia among adults in the United States." (PMID 39969369, 2024). "The findings indicated that CRP and BMR might potentially act as mediators in the causative relationship between glucosamine and sarcopenia proxy indicators." (PMID 39764251, 2024). "Based on the multivariable restricted cubic spline model, CRP levels showed a nonlinear association with sarcopenia (P < .001)." (PMID 39969369, 2024). "It was reported that C-reactive protein (CRP) was associated with degenerative changes, so CRP may be a driving factor of sarcopenia." (PMID 38395763, 2024). "Additionally, the adjusted OR of sarcopenia of 1.86 (95% CI, 1.37–2.51; P < .001) was obtained for participates with CRP levels ≥ 1.8, using 2-piecewise regression models." (PMID 39969369, 2024). "The high percentage of patients in acute care hospitals and with elevated CRP levels may indicate that acute illness leads to acute sarcopenia." (PMID 39275233, 2024). "Additionally, our findings demonstrated an inverse relationship between CRP levels and muscle mass and strength, further supporting the utility of CRP as an early biomarker for sarcopenia." (PMID 39502753, 2024). "In addition, patients with sarcopenia were more likely to have advanced stages of liver fibrosis (F3/F4: 59% vs. 30%, p < 0.05) and had significantly higher rates of C-reactive protein (CRP) (≥0.5 mg/dL) positivity, portal hypertension, and HCC." (PMID 38024081, 2023). "However, it appears that these two markers favor the appearance of sarcopenia and increase the production of acute-phase reactive proteins by the liver, such as C-reactive protein (CRP) or α1-antichimotrypsin (ACT)." (PMID 36672642, 2023). "According to several horizontal and longitudinal studies, sarcopenia is associated with high levels of proinflammatory cytokines, including tumor necrosis factor-α (TNF-α), interleukin-6 (IL-6), and C-reactive protein (CRP)." (PMID 38260146, 2023). "Sarcopenia is also associated with elevated levels of TNF-α, IL-6, and C-reactive protein, suggesting that appropriate treatment for RA may also reduce the development of sarcopenia." (PMID 37239687, 2023). "Using cut-offs for biomarkers and categories for presence or absence of sarcopenia, the results showed that only CRP was significantly associated with the presence or absence of sarcopenia (p = 0.01)." (PMID 37906352, 2023). "The results of the ROC analysis of the indicators which are likely to be important in the diagnosis of the inflammaging in sarcopenia, i.e., cfDNA, CRP and IL-1β ranged from 0.6 to 0.7, which can be considered as a potential diagnostic value for clinical prognosis for older patients." (PMID 37465171, 2023). "Furthermore, the group diagnosed with sarcopenia had a significant increase in systemic inflammatory markers, including CRP and IL-6." (PMID 38026977, 2023). "However, when the cut-off for sarcopenia was analysed by ANOVA in relation to the continuous variables of the biomarkers, the results showed that sarcopenia correlated significantly with albumin (p < 0.01), Hb (p < 0.01), TNFα (p = 0.02) and CRP (p < 0.01)." (PMID 37906352, 2023). "In our study, both high CRP level and sarcopenia were detected in 54.2% of patients." (PMID 35575465, 2022). "Moreover, they showed a link between the incidence of sarcopenia and disability, C-reactive protein (CRP) level and age." (PMID 35330186, 2022).
sarcopenia (continued). "With a large older population (6,172 participants aged 60 years and above), high CRP levels were reported in participants with possible sarcopenia (defined as low muscle strength and/or decreased physical performance) compared to participants without sarcopenia." (PMID 35570546, 2022). "Furthermore, we applied SHAP values to interpret the LightGBM model, highlighting the significance of BMI, gender, height, and CRP in the diagnosis of sarcopenia in Crohn’s disease." (PMID 36612977, 2022). "Furthermore, we applied SHAP values to interpret the LightGBM model, indicating the significance of BMI, gender, height, and CRP in the diagnosis of sarcopenia among CD patients." (PMID 36612977, 2022). "However, the prevalence of sarcopenia and its relationship with CRP levels were in agreement with the values reported in several studies of 12.70% and high hs-CRP levels being linked to sarcopenia compared to low hs-CRP levels in older adults." (PMID 35570546, 2022). "In agreement with our results, a meta-analysis found that levels of CRP but not Interleukin 6 or tumor necrosis factor α were associated with sarcopenia." (PMID 35719155, 2022). "Moreover, admission to the Intensive Care Unit was more frequent (p= 0.04), and WBC (p = 0.01) and days of C Reactive Protein (CRP) above the upper normal limit during hospitalization (p < 0.001) were higher in patients with probable sarcopenia." (PMID 35250860, 2022). "Highly relevant variables including BMI, height, gender, and CRP could easily identify patients with sarcopenia based on Shapley values at a local (patient) level." (PMID 36612977, 2022). "The univariate analysis of the clinical and demographic characteristics for PFS identified male gender (HR 3.19), ECOG PS 2-3 (HR 2.04), smoking (HR 3.04), sarcopenia (HR 2.35), cranial metastasis (HR 2.20), liver metastasis (HR 2.92), and CRP > 6.5 mg/L (HR 2.46) as poor prognostic factors." (PMID 35575465, 2022). "Therefore, the present study aimed to determine the relationships and prediction of serum CRP levels in functional capacity and the components of sarcopenia among Thai older people." (PMID 35570546, 2022). "Secondly, we were lacking in some data, such as C-reactive protein, cachexia, sarcopenia, and KRAS mutation status, which were essential to survival." (PMID 35719977, 2022). "The present work evaluated how Peking prognostic score (PPS), the new prognostic index determined according to sarcopenia and lymphocyte-to-C-reactive protein ratio (LCR), was a prognostic factor for patients with gastric cancer liver metastases (GCLM) who received hepatectomy." (PMID 36245530, 2022). "Elevated concentrations of IL-6 and CRP are often detected in sarcopenia and SO." (PMID 35100595, 2022). "Overall, mean age, MELD score, lymphocyte count, NLR, TBIL, INR, CRP, IL-6, proportion of sarcopenia, and more than one complication were higher in the patients who experienced progression; conversely, the mean L3 SMI, platelet count, ALT, sodium, and AFP were lower (p < 0.05)." (PMID 35771410, 2022). "The prevalence of sarcopenia decreased as CRP increased (<1.2 mg/L: 26.9%, ≥5.3 mg/L: 19.2%)." (PMID 34836213, 2021). "The multivariable logistic regression models suggested a positive association of SII with sarcopenia and sarcopenic obesity, but a positive statistically significant association was not consistently observed for CRP." (PMID 34836213, 2021). "Accordingly, higher systemic concentrations of CRP may reflect higher adiposity in those with sarcopenia or sarcopenic obesity." (PMID 33853546, 2021). "In univariate regression models, disability was significantly associated with BMI (OR: 4.60, 95% CI: 2.28–9.30), sex (OR: 2.25, 95% CI: 1.13–4.47), CDAI (OR: 15.69, 95% CI: 3.54–69.42), BMI (OR: 4.60, 95% CI: 2.28–9.30), sarcopenia (OR: 3.40, 95% CI: 1.59–7.72), and CRP (OR:1.31, 95% CI: 1.05–1.64)." (PMID 34307398, 2021).
sarcopenia (continued). "Our study suggests that there is a positive association of CRP and SII with sarcopenia and sarcopenic obesity, which indicates that older vulnerable people with high systemic inflammation are more likely to have these conditions compared to counterparts with lower levels of inflammation." (PMID 34836213, 2021). "For example, a cross-sectional study conducted in the outpatient clinic found that NLR values were positively correlated with other inflammatory markers, such as CRP; and a higher NLR level was independently associated with an increased risk of EWGSOP defined sarcopenia." (PMID 33160322, 2020). "Subjects with sarcopenia have elevated concentrations of C-reactive protein and inflammatory cytokines, which may promote skeletal muscle catabolism." (PMID 32351917, 2020). "Selected parameters for muscle tissue computed tomography-scan derived and matched with BMI allowed to define the condition of sarcopenia; the mGPS was instead assessed through the level of C-reactive protein (CRP) and albumin (high mGPS was equal to CRP > 1.0 mg/dL and albumin < 3.5 g/dL)." (PMID 31766196, 2019). "Furthermore, according to a previous study, participants with sarcopenia have an increased level of serum inflammatory parameters,especially for CRP levels." (PMID 31269909, 2019). "In multivariable analysis, weight loss >5% (HR 2.8), reduction in SM >5% (HR 5.5), an increase in CRP (HR 2.2) or CA 19.9 (HR 1.9), and resection (HR 0.4) remained independently associated with survival, whereas classical cachexia and sarcopenia did not." (PMID 31717736, 2019). "In univariate logistic regression analysis using potential confounders, the following factors were significantly associated with the odds of having sarcopenia: age, BMI, eGFRcr, DM, overall diuretic use, loop diuretic use, XO inhibitor use, UPCR ≥ 0.5 g/gCr, hemoglobin, log CRP, and exercise habit." (PMID 29447254, 2018). "Data from the literature show that some inflammatory markers such as IL6, CRP and tumor necrosis factor (TNF) alpha were associated with sarcopenia, and in patients with CKD, these markers were higher than in the patients with normal renal function and were associated with unfavorable outcomes." (PMID 28448584, 2017). "In addition, several clinical studies imply the relationship between serum CRP concentration and sarcopenia." (PMID 29259690, 2016). "There is a growing body of evidence suggesting that sarcopenia is a smoldering inflammatory state driven by cytokines and oxidative stress since elevated levels of interleukin-6 and C-reactive protein are often detected (see “Inflammation and AGING” in Data S1)." (PMID 22096509, 2011). "We speculate that CRP-mediated chronic systemic inflammation may lead to long-term skeletal muscle damage, and thereby contribute directly to sarcopenia." (PMID 20520725, 2010). "In those under 60 years of age, sarcopenia was independently associated with increased CRP in both non-obese (CRP ratio 1.13, 95% CI 1.01 to 1.30, p = 0.02) and obese individuals (CRP ratio 1.093, 95% CI 1.041 to 1.143, p = 0.002)." (PMID 22421977, 2010). "Our data also suggest that in young and middle-aged individuals (both obese and non-obese) sarcopenia is associated with greater inflammation (higher levels of serum CRP)." (PMID 22421977, 2010). "For severe sarcopenia, the RCS curve revealed a cutoff at log CRP = 0.489 separating the plots into two phases, with severe sarcopenia risk decreasing slightly for log CRP < 0.489 (OR: 0.82, 95% CI: 0.70–0.98) and increasing rapidly for log CRP > 0.489 (OR: 2.31, 95% CI: 1.94–2.74)." (PMID 40791098, 2025). "However, unlike our findings, previous research has linked higher CRP levels with sarcopenia, reporting elevated CRP levels in individuals with sarcopenia compared to those without while failing to adjust for potential confounding factors." (PMID 40708651, 2025).
sarcopenia (continued). "Therefore, we investigated whether CRP level was independently related to sarcopenia in adults from the 2015 to 2018 NHANES." (PMID 39969369, 2024). "Thus, sarcopenia may have a better prognostic value when combined with the C-reactive protein-to-albumin ratio." (PMID 38913646, 2024). "Although the baseline levels of serum albumin, C-reactive protein (CRP), and interleukin 6 (IL-6) were comparable between patients with and without sarcopenia, the development of sarcopenia was significantly associated with lower albumin levels and higher CRP and IL-6 levels." (PMID 38797769, 2024). "Consequently, our study focused on examining the link between CRP concentrations and sarcopenia." (PMID 39502753, 2024). "Furthermore, elevated concentrations of TNF-α, IL-6 and CRP are frequently identified in sarcopenia patients These cytokines probably trigger the activation of the ubiquitin-protease system and develop sarcopenia." (PMID 37932727, 2023). "Patients with peripheral arterial disease (PAD) are more likely to develop sarcopenia through an altered inflammatory process, probably mediated by the deregulation of multiple cytokine-related factors, such as the elevation of IL-6, an IL-1 receptor antagonist, fibrinogen, and CRP." (PMID 36672642, 2023). "Moreover, CRP has been previously related to sarcopenia in patients with CD." (PMID 37630805, 2023). "High levels of pro-inflammatory factors interleukin-6 (IL-6), tumor necrosis factor-α (TNF-α), and C-reactive protein (CRP) may induce sarcopenia by affecting protein balance synthesis, and dysregulation of the inflammation may also be involved in the pathophysiological mechanisms of MCI." (PMID 38148730, 2023). "Sarcopenia appeared to be related to several factors that may be involved in the prognosis, namely, extranodal involvement, prealbumin, alpha-1 acid glycoprotein, CRP, BMI, and NIS." (PMID 37058153, 2023). "In addition, the effects of sarcopenia and CRP level on erlotinib response were analyzed." (PMID 35575465, 2022). "Furthermore, we did not observe any remarkable association between inflammatory biomarkers including IL-6 (OR 1.15; 95% CI 0.31–4.28), TNF-α (OR 0.68; 95% CI 0.17–2.77), and hs-CRP (OR 2.39; 95% CI 0.87–6.55) and the presence of sarcopenia even after controlling for plausible confounders." (PMID 35361818, 2022). "In a second step, we compared the evolution of physical performance between faller and no-faller, between those with > 1 sarcopenia/fall risk factors vs. ≤ 1 indicator, and patients with the normal inflammatory indicator (CRP ≤ 30 mg/l and albumin ≥ 30 g/l), and those with subnormal value." (PMID 35186984, 2022). "In addition, CRP showed an inverse correlation with the R-leg-M (r = −0.41, p-value < 0.05) and a positive correlation with triceps skinfold thickness (r = 0.42, p-value < 0.05) in the sarcopenia group." (PMID 36291982, 2022). "The current study showed that higher levels of systemic inflammation (as indexed by CRP) were associated with sarcopenic obesity, which is supported by a recent meta-analysis that showed that sarcopenia is associated with higher CRP, but not with higher IL-6 or TNFα." (PMID 33853546, 2021). "Finally, we did not measure and adjust for inflammatory markers, such as C-reactive protein and IL-6, which were supposed to be associated with sarcopenia and psoriasis." (PMID 34722590, 2021). "Finally, CRP and IL-8 levels and adiponectin/leptin ratio may have prognostic value for the development of sarcopenia." (PMID 33566325, 2021). "However, a notable finding in our study was that variations in CRP levels did not affect the proposed effects of adherence to a healthy diet on sarcopenia risk." (PMID 34444973, 2021). "Therefore, our results suggest that it may be necessary to use a combination of the PhA and hs-CRP levels when testing models that predict sarcopenia, frailty, and/or mortality." (PMID 31775231, 2019).